RN7SL76P (RNA, 7SL, cytoplasmic 76, pseudogene)
Gene: Miscellaneous RNA gene on chromosome 7 (151,464,650 to 151,464,938, reverse strand). Ensembl gene ENSG00000241959.
Homologues: Orthologues: chimpanzee Metazoa_SRP (99% identical), macaque Metazoa_SRP (89% identical). Paralogues in human: RN7SL2 (80% identical), RN7SL1 (79% identical), RN7SL3 (78% identical), RN7SL220P (76% identical), RN7SL47P (76% identical), RN7SL709P (76% identical), RN7SL650P (76% identical), RN7SL655P (76% identical), RN7SL342P (75% identical), RN7SL530P (75% identical), RN7SL88P (75% identical), RN7SL444P (75% identical), and 703 more.